PAPOLA (poly(A) polymerase alpha)
Description:
Polymerase that creates the 3'-poly(A) tail of mRNA's. Also required for the endoribonucleolytic cleavage reaction at some polyadenylation sites. May acquire specificity through interaction with a cleavage and polyadenylation specificity factor (CPSF) at its C-terminus.
Synonyms: PAP-alpha; PAP
Tractability: PROTAC: UniProt records ubiquitination sites on it; ubiquitination databases record sites on it; its protein half-life has been measured.
Gene: Protein-coding gene on chromosome 14 (96,501,433 to 96,567,118, forward strand). Ensembl gene ENSG00000090060.
Subcellular location: Cytoplasm; Nucleus
Subcellular location (Human Protein Atlas): Nucleoplasm
Pathways (Reactome):
Metabolism of RNA: Processing of Intronless Pre-mRNAs; mRNA 3'-end processing; mRNA Polyadenylation
Disease: Dengue Virus-Host Interactions
Gene expression (Transcription): RNA Polymerase II Transcription Termination
Gene Ontology:
Molecular function: poly(A) RNA polymerase activity; protein binding; ATP binding; magnesium ion binding; manganese ion binding; nucleotidyltransferase activity; RNA binding
Biological process: co-transcriptional mRNA 3'-end processing, cleavage and polyadenylation pathway; mRNA 3'-end processing; RNA 3'-end processing
Cellular component: cytoplasm; nucleoplasm; nucleus
Genetic constraint (gnomAD): Loss-of-function variants: 3 observed, 36.34 expected, observed/expected ratio (o/e) 0.0825, 90% interval 0.037 to 0.21. The upper end of that interval is the gene's LOEUF score, 0.21, which puts it in group 1 of 6, group 1 being the genes least tolerant of losing a copy. Missense variants: 235 observed, 388.76 expected, observed/expected ratio (o/e) 0.6, 90% interval 0.54 to 0.67. Synonymous variants: 138 observed, 140.87 expected, observed/expected ratio (o/e) 0.98, 90% interval 0.85 to 1.13.
Homologues: Orthologues: chimpanzee PAPOLA (100% identical), macaque PAPOLA (99% identical), dog PAPOLA (98% identical), rabbit PAPOLA (98% identical), mouse Papola (95% identical), pig PAPOLA (95% identical), rat Papola (95% identical), guinea pig PAPOLA (94% identical), tropical clawed frog papola (82% identical), zebrafish papola (70% identical), Drosophila melanogaster hrg (48% identical), Caenorhabditis elegans pap-1 (37% identical), and 2 more. Paralogues in human: PAPOLB (72% identical), PAPOLG (60% identical).
Diseases named in the same sentence as PAPOLA in open-access papers:
PAPOLA is named in the same sentence as 19 diseases in open-access papers, as found by Europe PMC text mining. Sharing a sentence is not in itself a finding about the gene and the disease. The quoted sentences say what the papers report.
chronic eosinophilic leukemia (2 papers, 2022 to 2025). "Factor interacting with PAPOLA and CPSF1 (FIP1L1), fused with platelet-derived growth factor receptor α (PDGFRα), has been linked to several hematologic malignancies (hypereosinophilic syndrome, chronic eosinophilic leukemia, systemic mastocytosis)." (PMID 35494081, 2022). "The most sensitive cell line was the chronic eosinophilic leukemia cell line EoL-1 (IC50 = 59 nmol/L), expressing a fusion gene of Factor Interacting with PAPOLA and CPSF1 (FIP1L1) and platelet-derived growth factor receptor α (PDGFRα)." (PMID 41199836, 2025).
cognitive deficits (1 paper, 2024). "An increase in A8RNA levels and a corresponding decrease in C9orf72 transcription, coupled with reduced PAPOLA activity, could contribute to cognitive deficits after aSAH by hindering the activation of stress response pathways." (PMID 39726593, 2024).
dementia (1 paper, 2024). Loss of intellectual abilities interfering with an individual's social and occupational functions. "In this network, DOK3 and PAPOLA, both upregulated, were identified as potential hub genes associated with increased dementia risk post-SAH through apoptotic pathways." (PMID 39726593, 2024). "Recent studies have linked PAPOLA to neurological diseases such as dementia, which may complicate the course of aSAH." (PMID 39726593, 2024). "Additionally, GSEA indicated that upregulation of DOK3 and PAPOLA affected crucial biological pathways potentially linked to processes like immune response modulation and apoptosis, with implications for conditions such as dementia." (PMID 39726593, 2024). "To investigate the miRNA-mRNA regulatory network involved in aSAH-induced dementia, we focused on DOK3 and PAPOLA as central genes potentially linked to disease progression." (PMID 39726593, 2024). "This study aimed to explore the relationship between aSAH and the increased risk of dementia, emphasizing the roles of DOK3 and PAPOLA as critical genes in this process." (PMID 39726593, 2024). "Further research is warranted to explore PAPOLA’s impact on cognition following aSAH and to assess its potential as a therapeutic target for preventing post-aSAH dementia." (PMID 39726593, 2024). "Understanding the molecular dysfunction of DOK3 and PAPOLA in aSAH patients may provide valuable insights into the deregulated molecular pathways that contribute to dementia development, thereby suggesting novel therapeutic targets." (PMID 39726593, 2024). "The role of PAPOLA in post-aSAH dementia may be tied to its involvement in gene expression and mRNA stability, both critical for neuronal function and brain repair after injury." (PMID 39726593, 2024). "Gene Set Enrichment Analysis (GSEA) suggested that DOK3 and PAPOLA might influence both SAH and dementia through apoptotic pathways, which aligns with literature indicating dysregulated apoptosis in neurodegenerative diseases and neurovascular injury." (PMID 39726593, 2024).
glioblastoma (1 paper, 2024). The most malignant astrocytic tumor (WHO grade IV). "In this study, we investigated the role of DOK3 and PAPOLA in tumor prognosis using U251MG glioblastoma cells." (PMID 39726593, 2024). "Patients with low PAPOLA expression also demonstrated better survival rates, further suggesting the prognostic importance of these genes in glioblastoma." (PMID 39726593, 2024).
glioma (1 paper, 2024). A benign or malignant brain and spinal cord tumor that arises from glial cells (astrocytes, oligodendrocytes, ependymal cells). "The roles of DOK3 and PAPOLA as central players in multiple diseases, including glioma, are further supported by existing research." (PMID 39726593, 2024).
kidney damage (1 paper, 2021). "The other six markers, CDC5L, HNRNPU, NUDT21, PAPOLA, POLR2B, and WBP4, were all negatively correlated with GFR, indicating that these genes may aggravate kidney damage in patients with LN." (PMID 34557492, 2021).
ovarian tumor (1 paper, 2024). "The role of genes encoding such proteins, LUC7L2, MRPL46, MRPL14, PARP4, STRAP, and PAPOLA, in ovarian tumor development has already been investigated in the literature." (PMID 39456618, 2024).
Stillbirth (1 paper, 2018). Death of the fetus in utero after at least 22 weeks of gestation. "Second, the top SNP in chromosome 14 associated with the number of stillbirths is 99 kb away from the PAPOLA gene encoding a poly-A tail polymerase that affects mRNA stability and nuclear export." (PMID 30188897, 2018). "Fourteen SNPs between the PAPOLA (poly(A) polymerase alpha) and the VRK1 (vaccinia related kinase 1) genes were associated with the number of stillbirths in the continuously married subset (p ≥ 8.38×10−9)." (PMID 30188897, 2018). "Although it is not a species consumed by ethnic Tibetan women in this region, our results raise the possibility that the PAPOLA SNPs may affect the stillbirth phenotype by interacting with an exposure to C. sinensis during pregnancy." (PMID 30188897, 2018).
tauopathies (1 paper, 2025). "Overall, RBPs enriched in disease-associated modules included the previously validated CHD4, MACROH2A1, SAFB, WDR82, and PAPOLA proteins, highlighting their potential relevance to tauopathies." (PMID 41205924, 2025).
cancer (2 papers, 2016 to 2024). A tumor composed of atypical neoplastic, often pleomorphic cells that invade other tissues. "DOK3, involved in immune signaling and apoptosis regulation, and PAPOLA, crucial for mRNA stability and linked to cancer, appear to be key components of the pathways through which SAH may parallel the effects observed in VaD." (PMID 39726593, 2024). "This comprehensive analysis provides a solid foundation for future studies to elucidate the precise mechanisms through which DOK3 and PAPOLA influence immune infiltration in cancer." (PMID 39726593, 2024). "In our pan-cancer analysis, we examined the expression of DOK3 and PAPOLA across various cancer types." (PMID 39726593, 2024). "Furthermore, a pan-cancer analysis revealed that DOK3 and PAPOLA exhibit differential expression across various cancer types, reflecting their involvement in fundamental cellular processes like apoptosis and inflammation." (PMID 39726593, 2024). "The consistent findings across different methodologies for DOK3 and PAPOLA emphasize their importance in shaping the immune landscape of various cancers, suggesting that these genes could be critical targets for therapeutic interventions to modulate tumor immunity." (PMID 39726593, 2024).
metabolic disease (1 paper, 2024). A congenital disorder (due to inherited enzyme abnormality) or acquired (due to failure of a metabolically important organ) disorder resulting from an abnormal metabolic process. "Similarly, elevated PAPOLA levels have been associated with activating apoptosis-related pathways and downregulating pathways involved in metabolic diseases, biooxidation, the respiratory electron transport chain, and alanine/aspartate metabolism." (PMID 39726593, 2024).
PAPOLA also shares sentences with these, for which no sentence is quoted: hypereosinophilic syndrome (1 paper); neurodegenerative disease (1); neurological diseases (1); ovarian carcinoma (1); subarachnoid hemorrhage (1); systemic mastocytosis (1); Tumor (1); vascular dementia (1).